TAL1 (TAL bHLH transcription factor 1, erythroid differentiation factor)
Description:
Implicated in the genesis of hemopoietic malignancies. It may play an important role in hemopoietic differentiation. Serves as a positive regulator of erythroid differentiation (By similarity).
Synonyms: TAL-1; bHLHa17; SCL; TCL5
Tractability: PROTAC: UniProt records ubiquitination sites on it; ubiquitination databases record sites on it.
Gene: Protein-coding gene on chromosome 1 (47,216,290 to 47,232,225, reverse strand). Ensembl gene ENSG00000162367.
Subcellular location: Nucleus
Subcellular location (Human Protein Atlas): Nucleoplasm
Pathways (Reactome):
Developmental Biology: Transcriptional regulation of granulopoiesis
Disease: Dengue Virus-Host Interactions
Gene expression (Transcription): RUNX1 regulates transcription of genes involved in differentiation of HSCs
Gene Ontology:
Molecular function: chromatin binding; DNA-binding transcription factor activity; E-box binding; enzyme binding; histone deacetylase binding; protein binding; RNA polymerase II-specific DNA-binding transcription factor binding; DNA-binding transcription factor activity, RNA polymerase II-specific; RNA polymerase II cis-regulatory region sequence-specific DNA binding; transcription cis-regulatory region binding; DNA binding; protein dimerization activity
Biological process: basophil differentiation; erythrocyte differentiation; megakaryocyte differentiation; positive regulation of cell division; positive regulation of chromatin organization; positive regulation of DNA-templated transcription; positive regulation of erythrocyte differentiation; positive regulation of mitotic cell cycle; positive regulation of protein-containing complex assembly; positive regulation of transcription by RNA polymerase II; cell fate commitment; embryonic hemopoiesis; hemopoiesis; regulation of transcription by RNA polymerase II
Cellular component: chromatin; nucleoplasm; nucleus; transcription regulator complex; cytosol; protein-containing complex
Genetic constraint (gnomAD): Loss-of-function variants: 7 observed, 13.27 expected, observed/expected ratio (o/e) 0.53, 90% interval 0.3 to 0.99. The upper end of that interval is the gene's LOEUF score, 0.99, which puts it in group 4 of 6, group 1 being the genes least tolerant of losing a copy. Missense variants: 373 observed, 321.87 expected, observed/expected ratio (o/e) 1.16, 90% interval 1.06 to 1.26. Synonymous variants: 174 observed, 141.72 expected, observed/expected ratio (o/e) 1.23, 90% interval 1.08 to 1.39.
Homologues: Orthologues: chimpanzee TAL1 (99% identical), macaque PDZK1IP1 (97% identical), pig TAL1 (95% identical), dog TAL1 (94% identical), mouse Tal1 (93% identical), rat Tal1 (92% identical), rabbit TAL1 (85% identical), guinea pig TAL1 (55% identical), tropical clawed frog tal1 (55% identical), zebrafish tal1 (54% identical). Paralogues in human: LYL1 (31% identical), TAL2 (17% identical), NHLH2 (15% identical), NHLH1 (15% identical).
Diseases named in the same sentence as TAL1 in open-access papers:
TAL1 is named in the same sentence as 82 diseases in open-access papers, as found by Europe PMC text mining. Sharing a sentence is not in itself a finding about the gene and the disease. The quoted sentences say what the papers report.
leukemia (69 papers, 2009 to 2025). A malignant (clonal) hematologic disorder, involving hematopoietic stem cells and characterized by the presence of primitive or atypical myeloid or lymphoid cells in the bone marrow and the blood. "Overall, the RNA-seq analysis supports our previous finding that USP7 is implicated in the negative regulation of TAL1-dependent leukemia growth." (PMID 35205126, 2022). "A small module on chromosome 1 contains the lncRNA CYP4A22-AS1), also known as ncRNA-a3, which has been shown to act as enhancer for its flanking stem cell leukemia-associated gene TAL1, and we recapitulate the direct interaction between them." (PMID 31142264, 2019). "ITGB5 has been shown to contribute to tumor development in breast cancer, epithelial-mesenchymal transition and tumor potential in carcinoma cells and TAL1 is T-cell pro-oncogene with over-expression associated with development of leukemia." (PMID 30586396, 2018). "In this context, E-proteins act as tumor suppressors, as several groups have shown that E2a-deficient mice develop T-cell lymphoma and that this deficiency accelerates leukemia onset and progression in Tal1-transgenic mice." (PMID 29034206, 2017). "Therefore, while TAL1:E protein or LYL1:E protein dimers in T-ALL regulate leukemia-associated genes, expression of TAL1 and LYL1 can also interrupt the function of E protein homodimers." (PMID 35514954, 2022). "We treated 6-week WT or leukemia-prone Tal1, Lmo2, and Tal1/Lmo2 mice expressing the reporter with doxycycline for 6 weeks to induce H2B-GFP expression." (PMID 38553571, 2024). "Again, we observed a remarkable dichotomy in age estimates among the HOXA and TLX3 subtypes versus the TAL1 subtypes, revealing leukemias derived from early developmental stages to have age estimates ranging from ~100–200 years old." (PMID 38867059, 2024). "We next utilized scRNA-seq to uncover transcriptional heterogeneity among the L-IC-containing DN3 population within the context of Tal1/Lmo2-induced primary mouse leukemias, T-ALL#1 and T-ALL#2." (PMID 38553571, 2024). "It is worth noting that PADI4 acts as a co-regulator of Tal1 in leukaemia, where it counteracts transcriptionally repressive histone arginine methylation via histone citrullination." (PMID 37778387, 2023). "Overall, we revealed that the “TAL1-TSPAN32-PTEN” signaling axis played a negative regulatory role in Ph+ leukemias." (PMID 36854750, 2023). "This is of particular interest because LMO proteins are overexpressed in approximately 10% of T-ALLs and these leukemias frequently have TAL1 overexpression." (PMID 35514954, 2022). "Experiments in human T-ALL cell lines have been vital to elucidating the core components of the TAL1 complex in leukemia." (PMID 35514954, 2022). "Further, LMO2 is frequently overexpressed in TAL1 expressing leukemias but in LMO2 transgenic mice TAL1 is dispensable for leukemogenesis." (PMID 35514954, 2022). "TAL1 positive leukemias frequently express CD4 and CD8 and have a cortical phenotype similar to what is observed in E2a-/- mice." (PMID 35514954, 2022). "Microarray analysis revealed that LMO2 expressing thymocytes have higher Lyl1 expression compared to wild type thymocytes indicating a potential feed-forward mechanism reminiscent of the mechanism seen in TAL1 expressing leukemias." (PMID 35514954, 2022). "It is also notable that Lck-TAL1 promotes leukemia in a dose-dependent manner that is augmented by deletion of the E proteins encoded by Heb/Tcf12 indicating that E protein dose is a major determinant of leukemogenesis in this model." (PMID 35514954, 2022). "NOTCH1 is constitutively activated in a majority of T-ALL, including those that overexpress TAL1, and in leukemias from E2a-/- mice." (PMID 35514954, 2022). "The role of TAL1 in hematopoiesis, leukemia, and endothelial cell generation is well-known, yet this is the first demonstration of Notch1-induced expression of TAL1 in GSCs." (PMID 34771555, 2021).
leukemia (continued). "Other gene expressed at the initial stage of hematopoiesis is the stem cell leukemia gene (SCL/TAL1)." (PMID 34736527, 2021). "The blockade of adhesion of CML-initiating cells to E-selectin expressed on the bone marrow endothelium increased cell cycle progression and the SCL/TAL1 signaling axis in leukemia cells, improving the efficacy of imatinib treatment." (PMID 33435150, 2021). "For example, LYL1, an oncogene that is aberrantly expressed in diverse subtypes of AML, assembles with MYB in leukemia cells examined in our study, similar to its functional homologue TAL1 in cases of T-ALL." (PMID 33527899, 2021). "Given that TAL1 is required for both hematopoietic and leukemia cell survival, we further examined if −31CBS−/− affected cell cycle progression of K562 cells." (PMID 32086528, 2020). "The top 15 TFs enriched within the K562 cell associated pattern include TAL1, EGR1, RREB1 and NFE2 which have all been associated with leukemia or, in the case of NFE2, is an erythroid nuclear factor." (PMID 32392348, 2020). "Consistent with this notion, CRISPR-mediated inversion of −31CBS disrupts an existing TAL1 promoter/enhancer interaction and inhibits TAL1 expression in T-ALL cells leading to interfering leukemia progression." (PMID 32086528, 2020). "TAL1 is a noteworthy hit, as K562 cells were used to establish TAL1 as a driver of leukemia, thus providing support for the validity of this approach." (PMID 32392348, 2020). "Both are GABAergic and can be distinguished based on the combinatorial expression of highly specific TFs: Forkhead Box A2 (Foxa2), GATA-binding factor 2/3 (Gata2/3), and Stem cell leukemia/T-cell acute leukemia 1 (Scl/Tal1)." (PMID 31641138, 2019). "Changes in gene expression following Bcor mutation in the non-transformed and malignant settings were significantly correlated, with key TFs Hoxa7, Hoxa9 and Tal1 also upregulated in the context of leukaemia." (PMID 30902969, 2019). "Among them, the stem cell leukemia gene (Scl/Tal1) is a central regulator of primitive hematopoiesis." (PMID 31101894, 2019). "More recently, PTEN loss has been analyzed in human T-ALL samples displaying the stem cell leukemia (SCL)/TAL1 interrupting locus (STIL) protein/TAL1 fusion product that were xenografted in mice and compared with specimens collected at diagnosis." (PMID 31064074, 2019). "These T-ALLs cluster with TAL1/LMO2-rearranged mature leukemias based on their gene expression signature." (PMID 30304769, 2018). "For all cell types, co-occurring TF pairs are not just combinations of the single TFs, moreover the co-occurring TF pairs include more cell-type specific TFs such as KLF4 and cMYC in ESCs or tumor-related genes STAT5 and TAL1 in leukemia." (PMID 30142147, 2018). "Given the position of the STIL-TAL1 fusion in leukaemia evolution, therapies targeting the TAL1 regulatory complex are worthy of further investigation." (PMID 29556024, 2018). "Many of the transcription factors that are important in HSCs are known to be causative of leukemia when deregulated, for example, RUNX1, MLL, SCL/TAL1 and LMO2." (PMID 28883990, 2017). "Tal1 and Lmo1/2 transgenic mice show an increased number of thymic progenitors that can generate leukemia, indicating that these oncogenic transcription factors are capable of inducing LIC ability in immature thymocytes." (PMID 29034206, 2017). "Our observations open the possibility of a regulatory loop between transcriptional regulation of PRKACB isoform expression and the modification status of TAL1 in differentiation and leukemia." (PMID 29069738, 2017). "One of the most commonly used T-ALL mouse models in the study of LICs is the Tal1 transgenic mouse model; approximately 30% of these mice develop leukemia after a long latency period." (PMID 29034206, 2017). "The majority of T-ALL patients with LMO ectopic expression also overexpress TAL1 and both transcription factors cooperate to induce leukemia in transgenic mice." (PMID 26882564, 2016).
leukemia (continued). "We then reasoned that if these miRNAs play a role in TAL1 over-expression in T-ALL their levels should be decreased in primary leukemia cells as compared to normal developing T-cells." (PMID 26882564, 2016). "TAL1-positive leukemias show the transcriptional upregulation of CD3 and TCR genes, developmental arrest in DP stage, and an overexpression of antiapoptotic gene Bcl2." (PMID 25866806, 2015). "This enhancer also has interactions with the promoter of GALNT5 and appears to be bound by a number of factors in K562 including GATA2, PML, TAL1 and BCL3, all of which have been implicated in the leukemia or other forms of cancer." (PMID 26576536, 2015). "TAL1/SCL induces leukemia by inhibiting the transcriptional activity of E47/HEB and interfering with several E47/HEB target genes critical for the thymocyte differentiation." (PMID 25866806, 2015). "In this study, c-Myc abrogation depleted leukemia LICs and prolonged survival in a Notch1 mutant Tal1/Lmo2 T-ALL mouse model." (PMID 25072021, 2014). "Tal2, which belongs to the same family of transcription factors as Tal1 and Lyl1, is also involved in human leukaemia." (PMID 24086757, 2013). "The basic helix-loop-helix transcription factors Tal1 and Lyl1 play a major role in the regulation of gene expression in the hematopoietic system and are involved in human leukemia." (PMID 24086757, 2013). "Our “in vitro” transduction protocol of Tal-1−/− and Runx1−/− differentiating ESCs could also be used to detect differences in the activities of mutated forms of these genes that are found in acute leukemia, therapy-derived leukemia, myelodysplastic syndrome, and chronic myelomonocytic leukemia." (PMID 23922928, 2013). "In leukemia, TAL1 (T-cell acute lymphocytic leukemia 1) activity is significantly correlated with patient survival." (PMID 19442316, 2009). "Finally, CD53 is overexpressed in Lmo2 mouse leukemias and was shown to protect human TAL1+ JURKAT cells from apoptosis." (PMID 38553571, 2024). "At the end of the pulse-chase period, a subset of Tal1 or Tal1/Lmo2 mice developed leukemia." (PMID 38553571, 2024). "The role of Tal1 in leukemia has been reported previously by multiple studies." (PMID 36923792, 2023). "Studies into the mechanisms of TAL1 deregulation in these patients revealed small insertions (<20bp) in a region 8kb upstream of TAL1 that create a de novo MYB binding site that results in strong enhancer activity in these leukemias." (PMID 35514954, 2022). "TAL1-dependent genes include MYB, which positively regulates cell cycle and anti-apoptotic genes, TRIB2, which supports the survival of T-ALL cell lines, and ARID5, a gene associated with a variety of leukemias." (PMID 35514954, 2022). "However, LYL1+ and TAL1+ leukemias have unique gene expression profiles and LYL1+ leukemias tend to be related to immature CD4-CD8- T cell progenitors." (PMID 35514954, 2022). "T-LICs were mostly studied in genetically engineered mouse models of T-ALL, among which, the T-cell acute lymphocytic 1 (TAL) basic helix-loop-helix (bHLH) transcription factor 1 (Tal1)-induced mouse model stands out, since 28% of the Tal1 transgenic mice develop leukemia." (PMID 36428753, 2022). "Among these were RUNX1, MYB, and TAL1, 3 out of 8 DE genes (Fisher Exact test, odds ratio = 93, p = 2 × 10−5) that have previously been identified as part of a core transcriptional circuitry important to our leukemia model system." (PMID 33526072, 2021). "Thus, our data reveal that the TAL1 +19 enhancer acts not only as stem cell enhancer, but also as a leukemia specific enhancer to activate the TAL1 in T-ALL." (PMID 32086528, 2020). "Upregulation of Tal1 in T-cells also led to leukemia in mice." (PMID 32086528, 2020). "However, in TAL1-expressing T-ALL cells, the leukemia-prone TAL1 promoter-IV specifically interacts with the +19 stem cell enhancer located 19 Kb downstream of TAL1 and this interaction is disrupted by the −31CBS inversion in T-ALL cells." (PMID 32086528, 2020).
leukemia (continued). "The extensive body of evidence of TAL1 participation in the development ofT-cell leukemia suggests that inhibitors of this protein, as well as inhibitorsof the associated signaling cascades, can be used as promising therapeuticagents to treat leukemia characterized by an abnormal activity of TAL1." (PMID 29713515, 2018). "TF_3 contained TFBSs for GATA1/2 and TAL1, essential in hematopoietic and leukemia cells." (PMID 28700586, 2017). "Our results suggest that miR-146b-5p is a functionally relevant microRNA gene in the context of T-ALL, whose negative regulation by TAL1 and possibly other oncogenes contributes to disease progression by modulating leukemia cell motility and disease aggressiveness." (PMID 27550837, 2016). "In order to test whether JQ1 interferes with leukemia initiation and reduces LICs, Tal1/Lmo2 mouse T-ALLs were transplanted into syngeneic recipients and vehicle or JQ1 administered for 3 weeks." (PMID 25072021, 2014). "Notably, these leukemias often present with activating NOTCH1 mutations, suggesting that enhanced NOTCH signaling and aberrant TAL1, LYL1, LMO1, and/or LMO2 expression are collaborative events in the multistep pathogenesis of T-ALL." (PMID 25522333, 2014). "Thus, our data reveal that the +19 stem cell enhancer located 19 Kb downstream of the TAL1 gene may also drive TAL1 expression in T-ALL leukemia." (PMID 32086528, 2020). "Thus, we envision that deregulation of the TAL1/ miR-17-92 axis could be mechanistically important for leukemia/lymphoma." (PMID 33293632, 2020). "In K562, the transcription factor E2F6, which might function as a repressor, is enriched in K562 single enhancers, while transcription factors STAT5, TAL1 and GATA2, which are all associated with growing culture and differentiation of leukemia cell, are significantly enriched in redundant enhancers." (PMID 30563465, 2018). "We initially assumed that the transactivation of the TetO-Stat5 transgene by the MMTV-tTA might not have been efficient enough, and we, therefore, crossed both TetO-Stat5 responder lines with Eμ-tTA and Tal1-tTA transgenics that have been utilized to generate multiple leukemia and lymphoma models." (PMID 23565285, 2013). "TAL1 is a master oncogenic driver in a major subset of T-ALL, and LMO1 is a frequent cofactor in TAL1-driven leukemias." (PMID 41007654, 2025). "In mouse models, NOTCH1 mutations did not initiate T-ALL, but their collaboration with oncogenes such as TAL1/SCL, ZMIZ1 and LMO2 led to the induction of leukemia." (PMID 36077822, 2022). "Expression of Lmo2 accelerates the onset of leukemia in Tal1 transgenic mice, and LMO1/LMO2 are commonly expressed in human TAL1-driven T-ALL." (PMID 34501239, 2021). "We previously showed that these pre-LSCs are driven by the SCL/TAL1 and LMO1 oncogenes, which depend on NOTCH1-MYC pathways, and are resistant to chemotherapeutic drugs used against leukemia (doxorubicin, camptothecin and dexamethasone)." (PMID 31196146, 2019). "A subsequent study by Kelliher and her colleagues utilizing the Tal1/Lmo2 mouse model of T-ALL also showed that the DN3 and DN4 populations of leukemia cells possess LIC properties and drive T-ALL leukemogenesis." (PMID 29034206, 2017). "For example, CRISPR/Cas9‐mediated deletion (191 bp) of −7.5 kb upstream regions of TAL1, which is bound by the transcription factor MYB, reduced the expression of TAL1 by ~85% in human Jurkat leukemia cells." (PMID 28255028, 2017). "In the present study, we show that miR-146b-5p is a functionally relevant TAL1 downstream microRNA target gene, whose downregulation contributes to T-ALL by impacting on leukemia cell motility in vitro and disease aggressiveness in vivo." (PMID 27550837, 2016). "Most intriguingly, this insertion occurred in a pediatric SCID-X1 patient who developed a leukaemia secondary to retroviral reinsertion (in front of LMO2, a known TAL1-cooperating oncogene) following gene therapy." (PMID 25615415, 2015).